PHB2 (prohibitin 2)
Diseases named in the same sentence as PHB2 in open-access papers (continued):
Sharing a sentence is not in itself a finding about the gene and the disease.
schizophrenia (1 paper, 2023). A major psychotic disorder characterized by abnormalities in the perception or expression of reality. "The mitochondrial and nuclear protein Prohibitin 2 (PHB2) could be dysregulated in schizophrenia." (PMID 37046989, 2023). "However, the possible dysregulation of PHB2 in schizophrenia and its possible contribution to the cognitive symptoms observed in the pathology is still unknown." (PMID 37046989, 2023). "Furthermore, our findings suggest that PHB2 may be involved in the mechanisms deregulated by altered glutamate signaling pathways in the initial stages of the disorder and may contribute to the development of cognitive symptoms linked to the NMDAR hypoactivity state in schizophrenia." (PMID 37046989, 2023).
Stomach Adenocarcinoma (1 paper, 2024). "Additionally, PHB2 mRNA levels were analysed in the Stomach Adenocarcinoma (STAD) dataset obtained from the Cancer Genome Atlas (TCGA) through RNA-sequencing (RNA-seq) analysis." (PMID 38200519, 2024).
Zika virus infection (1 paper, 2024). "Importantly, mono-allelic knockout was sufficient to reduce >80 % of PHB2 expression, which led to phenotypic switching and the propensity to form foci but was insufficient to affect growth rate or to inhibit Zika virus infection." (PMID 39049926, 2024).
cancer (48 papers, 2009 to 2025). A tumor composed of atypical neoplastic, often pleomorphic cells that invade other tissues. "FL3 exerts a potent anti-cancer effect in vivo without causing major adverse events, and therefore, targeting PHB2 is a promising anti-cancer therapy." (PMID 38262996, 2024). "PHB2 exerts broad biological activities and has been reported as a critical mediator of cancer-associated signaling pathways in multiple cancers." (PMID 36782197, 2023). "The PHB2-IGFBP-6 binding on the cell membrane causes increased tyrosine phosphorylation of PHB2 at tyrosine 128 and 271 by insulin receptor kinase, which was found to be correlated with cancer cell migration." (PMID 37190120, 2023). "The existence of the PHB2 loss-of-function mechanism by the cancer-specific molecule BIG3 will contribute to novel drug discovery based on reactivation of the innate suppressive function of PHB2." (PMID 34285339, 2021). "PHB2 plays a role in cell survival and is implicated in various cancers and diseases." (PMID 40940954, 2025). "Collectively, these data indicate that PHB2 deficiency by siRNA treatment in RD cells impaired the ultrastructure of the nucleolus and mitochondria, likely contributing to the inhibition of RD cell proliferation and subsequent inhibition of the tumorigenicity of these cancer cells." (PMID 29367618, 2018). "A recent study found that inhibiting PHB2-mediated mitophagy using PHB ligands (e.g., FL3) or shPHB2 effectively blocked cancer cell proliferation, revealing that targeting PHB2-mediated mitophagy is a promising strategy for cancer therapy." (PMID 40536597, 2025). "PHB2 also plays a dual role in various cancer types, acting either as an oncogene or tumour suppressor." (PMID 38200519, 2024). "Prohibitin 2 (PHB2) exhibits opposite functions of promoting or inhibiting tumour across various cancer types." (PMID 38200519, 2024). "Given the intricate functional roles of PHB2 observed across various cancer types, further investigation is warranted to fully elucidate its specific role in each type of cancer." (PMID 38200519, 2024). "Given its oncogenic role in the majority of cancer types including GC reported here, PHB2 emerges as a promising target for innovative cancer treatments." (PMID 38200519, 2024). "This highlights an avenue for forthcoming research and development aimed at curbing PHB2’s crucial impact on cancer, underscoring the potential for future therapeutic breakthroughs." (PMID 38200519, 2024). "Nonetheless, our ongoing investigation unveils that, similar to its increased presence in various cancer types, PHB2 is elevated in GC tissues compared to nearby healthy gastric tissues and PHB2 fosters proliferation in GC cells through an innovative pathway." (PMID 38200519, 2024). "In most human cancers, overexpressed PHB2 enhances tumor progression, while in some cancers, it suppresses tumor progression." (PMID 37190120, 2023). "High expressions of PHB1 and PHB2 were reported in 1078 cell lines in the Cancer Cell Line Encyclopedia (CCLE) and were recognized as common essential genes in 1077 of the 1078 tested cell lines (Depmap.org/Portal)." (PMID 37190120, 2023). "It was reported that PHB1 and PHB2 expression levels are high in most cancer types, for both mRNA and protein." (PMID 37190120, 2023). "As PHB2 promotes tumor progression and contributes to therapeutic resistance in most cancer types, it is a promising therapeutic target." (PMID 37190120, 2023). "Since PHB2 is overexpressed in pancreatic cancer, it is a potential new target for regulating Hes1 in future cancer treatments." (PMID 37190120, 2023). "The 3′-UTR of PHB2 was also targeted by autoantibodies in BC, consistent with the gene’s cancer-relevant roles in oxidative phosphorylation, mitochondrial biogenesis and apoptosis." (PMID 37082114, 2022). "Knockdown of PHB2 in cancer cells induced the inhibition of cell proliferation through induction of cell cycle arrest and suppression of DNA synthesis." (PMID 34750284, 2022).
cancer (continued). "The results indicate that PHB2 was mainly diffused throughout the cytoplasm and membrane of the cancer cells." (PMID 33537079, 2021). "Increasing evidence shows that PHB2 is highly expressed in other cancer types; however, the effects of PHB2 in NSCLC are currently poorly understood." (PMID 33537079, 2021). "As a contributing factor in other cancer types, PHB2 has been reported to regulate multiple processes via different pathways involved in tumorigenesis." (PMID 33537079, 2021). "While evidence of a role for PHB1 overexpression has been reported in cancer progression, higher levels of PHB2 was found in proliferating cells, including neoplastic tissues." (PMID 31684984, 2019). "Most studies have confirmed differential expression of PHB1 and PHB2 in cancers compared to corresponding normal tissues." (PMID 29784973, 2018). "A lot of evidence demonstrated that PHB1 and PHB2 are involved in biological processes of cancer development, such as proliferation, apoptosis, and metastasis." (PMID 29784973, 2018). "As PHB1 and PHB2 have been shown to be differentially expressed in multiple cancers, PHB1 and PHB2 are potentially useful as new biomarkers and targets in cancer diagnosis and treatment." (PMID 29784973, 2018). "Prohibitins (PHB1 and PHB2) have been proposed to play important roles in cancer development and progression, however their oncogenic mechanism of action has not been fully elucidated." (PMID 29029444, 2017). "The present study was initiated to determine the role of PHB1 and PHB2 in T- and B-cell malignancies." (PMID 29029444, 2017). "In human breast cancer cells, the absence of brefeldin A-inhibited guanine nucleotide-exchange protein 3 (BIG3) promoted the translocation of PHB2 to the nucleus after estradiol stimulation and resulted in the suppression of cancer cell growth." (PMID 26091791, 2015). "Silencing or abrogation of PHB2 induces apoptosis and reduces proliferation in a variety of cancer cells." (PMID 25200342, 2014). "Many of them such as Tumor protein D52, Prohibitin-2, Nucleophosmin, Elongation factor Tu(EF-Tu) have been previously reported as differentially expressed in PCa and closely related to oncogenesis and cancer progression." (PMID 21504578, 2011). "Tyr128 in PHB2 has been identified as phosphorylation site during phospho-tyrosine profiling in cancer cells." (PMID 19238206, 2009). "PHB2 modulates various signaling pathways through its interactions with numerous functional proteins, thereby impacting the survival, proliferation, and migration of cancer cells." (PMID 38200519, 2024). "The context-dependent nature of PHB2’s role underscores its complexity, necessitating detailed investigations for a comprehensive understanding of its diverse contributions across different cancer types." (PMID 38200519, 2024). "As PHB2 is an oncogene in most cancer types, it is a promising target for cancer treatment." (PMID 37190120, 2023). "Instead, this review will focus on PHB2 and its role in cancer." (PMID 37190120, 2023). "Cancer therapy may benefit from targeting PHB2-mediated mitophagy via the PHB2-PARL-PGAM5-PINK1 axis." (PMID 37023088, 2023). "This leaves room for future research and development to inhibit PHB2’s critical function in cancer." (PMID 37190120, 2023). "All data above suggested that the cancer suppressive function of LacRNA is exerted through PHB2." (PMID 36782197, 2023). "In a 2018 review paper, expression of PHB1 and PHB2 was surveyed in 17 cancer types." (PMID 37190120, 2023). "PHB2 was reported as an oncogene by a variety of mechanisms in 12 cancer types." (PMID 37190120, 2023). "However, in many different cancer types, PHB2 is overexpressed and functions as either a tumor suppressor or an oncogene." (PMID 37190120, 2023). "There are three cancer types in which PHB2 functions as a tumor suppressor." (PMID 37190120, 2023).
cancer (continued). "Prohibitin 2 (PHB2) is highly conserved protein mainly in mitochondria, nucleus and plasma membrane, which is required for Parkin-induced mitophagy in mammalian cells and cancer cell proliferation and adhesion." (PMID 35692054, 2022). "PHB1 and PHB2 levels were higher in these cancer patients than in controls." (PMID 34868199, 2021). "Overexpression of PHB1 and PHB2 has been observed in blood-related cancers." (PMID 34868199, 2021). "Combined with previous studies on PHB2 in other cancer types, we speculate that PHB2 may exert its influence on tumorigenesis in NSCLC based on its intracellular localization, and new mechanisms may be implicated in the future." (PMID 33537079, 2021). "Lastly, in this study, we first found that ANT2 and PHB2 act upstream of TS; however, more work is required to unravel whether and how ANT2 and PHB2 are expressed and regulated in specific cancer tissues." (PMID 33652782, 2021). "Moreover, a correlation between PHB2 expression and patients' clinicopathologic characteristics has been observed, and PHB2 is regarded as an independent prognostic marker for these cancers 10-13." (PMID 33537079, 2021). "Furthermore, PHB2 depletion has been shown to inhibit cancer cell growth and metastasis and enhance apoptosis in vitro and in vivo 10-14." (PMID 33537079, 2021). "Additionally, this study discovered that a synthesized ligand for PHBs, FL3, suppressed cancer by inhibition of mitophagy by PHB2." (PMID 34868199, 2021). "In addition, a short peptide ERAP and a natural product xanthohumol were shown to target PHB2 directly and prohibit cancer progression in estrogen-dependent cancers." (PMID 29784973, 2018). "The involvement of PHB2 in the regulation of cancer cell proliferation has been reported." (PMID 29367618, 2018). "Furthermore, studies verified that PHB1 and PHB2 are involved in the biological processes of tumorigenesis, including cancer cell proliferation, apoptosis, and metastasis." (PMID 29784973, 2018). "Interestingly, preclinical evidence indicates that both PARP1 and PHB2/PHB are excellent therapeutic targets in cancer." (PMID 25200342, 2014). "However, PHB2 was discovered as a tumour suppressor in other cancer types." (PMID 38200519, 2024). "Therefore, targeting PHB2 appears to be a safer and more sufficient cancer treatment strategy." (PMID 37190120, 2023). "Thus, our study not only led to the discovery of the pleiotropic signaling of TS regulation by ANT2 and PHB2 but also constitutes a starting point for the design of novel TS targeting agents based on rabdosianone I analogs to provide opportunities for cancer treatment and prevention." (PMID 33652782, 2021). "In addition, membrane-localized PHB2 also promotes cancer cell migration." (PMID 29784973, 2018). "Therefore, it was unclear how PHB2 is inactivated in ERα-positive cancer cells." (PMID 26052702, 2015). "PHB2 in the plasma membrane directly contacts insulin-like growth factor binding protein 6 (IGFBP 6) and regulates cancer cell migration by activating MAP kinases, IGF1R (GALNT14/PHB2/IGF1R)." (PMID 38813101, 2024). "Given the established role of mitophagy in aging, neurodegeneration, cancer, and inflammation, the functions of PHB1 and PHB2 in mitophagy likely play a mechanistic role in these diseases." (PMID 36593241, 2023). "PHB2 modulators are useful to understand PHB’s function in a variety of physiological and pathological conditions, including cancer." (PMID 37190120, 2023). "In human cancer cell lines, Mel56 targets the inner mitochondrial integral membrane prohibitin proteins, PHB1 and PHB2." (PMID 36678474, 2023). "We immobilized rabdosianone I onto nano-magnetic beads and identified two mitochondrial proteins, adenine nucleotide translocase 2 (ANT2) and prohibitin 2 (PHB2), as the direct targets of rabdosianone I in cancer cells." (PMID 33652782, 2021).
cancer (continued). "BIG3 also binds to prohibitin 2 (PHB2), which is known to function as a repressor of many cancer-related pathways, including estrogen signaling." (PMID 34285339, 2021). "Several publications have showed differential expression of PHB1 and PHB2 in cancer cell lines compared to normal tissues, verifying that PHB1 and PHB2 are involved in biological processes of tumorigenesis, such as cancer cell proliferation." (PMID 33374179, 2020). "Considering the special localization and significant roles of prohibitin domain family proteins in cancer, the value of PHB1 and PHB2 in cancer treatment warrants further detailed study." (PMID 29784973, 2018). "Moreover, ERAP, a short synthetic peptide, and xanthohumol, a natural product from medical plants, were demonstrated to suppress cancer cell proliferation by targeting PHB224, 25, indicating that drugs targeting PHB1 and PHB2 may be a promising strategy for cancer treatment." (PMID 29784973, 2018). "The increase in four multifunctional proteins, prohibitin and prohibitin 2, annexin A5 and protein S100A4, has also been documented in cancers, contributing to tumorigenic processes such as cell proliferation, metastasis, angiogenesis and immune evasion." (PMID 29662647, 2018). "We demonstrated that stERAP-6 bound to cytoplasmic PHB2 and thus translocated PHB2, along with stERAP-6, to the nucleus, although it still remains to be clarified how stapled ERAP entered cancer cells and the precise factors affect this property." (PMID 28500289, 2017). "Capsaicin, a potential anticancer agent, can directly bind to PHB2 and induced the dissociation of PHB2 from adenine nucleotide translocator 2 (ANT2), thereby promoting the nuclear translocation of PHB2 and cancer cell apoptosis." (PMID 26091791, 2015). "We validated the knockdown effect of each KPNA (KPNA1, KPNA5, and KPNA6) on the interactions between endogenous PHB2 and nuclear ERα in BIG3-depleted cancer cells." (PMID 26052702, 2015). "PHB2 was also found to play a role as an estrogen receptor alpha repressor, which results in an overall negative effect on estrogen-dependent cancers like BC." (PMID 37082114, 2022). "However, PHB2 can interact with brefeldin A-inhibited guanine nucleotide-exchange protein 3 (BIG3) in BC, which captures PHB2 in the cytoplasm of cancer cells and thereby inhibits the suppressive ability of PHB2." (PMID 37082114, 2022). "However, most of the current knowledge concerning PHB proteins in cancers has been gleaned from studies with prohibitin 1 (PHB1), while studies on the effects of PHB2 have been limited to date, especially in NSCLC 34, 37-40." (PMID 33537079, 2021). "Additionally, numerous studies have observed a negative correlation between PHB2 expression and the prognosis of tumour patients in various cancer types." (PMID 38200519, 2024). "However, whether this regulation among PHB2, SHIP2, and NEDD4 might be applicable to other types of cancer remains to be defined." (PMID 38200519, 2024). "The results showed that the depletion of only BIG3 led to interactions between endogenous PHB2 released from BIG3 with nuclear ERα but that the depletion of BIG3 and KPNA1, KPNA5, and KPNA6 did not, indicating that PHB2 binding to nuclear ERα in cancer cells is KPNA-mediated." (PMID 26052702, 2015). "Researchers had identified ZNF703 as a cofactor of a nuclear complex covering DCAF7, PHB2 and NCOR2 through mass spectrometry and pointed out that ZNF703 expression could result in the activation of stem cell-related gene expression leading to an increase in cancer stem cells." (PMID 27764785, 2016).